ALB (albumin)
Diseases named in the same sentence as ALB in open-access papers (continued):
Sharing a sentence is not in itself a finding about the gene and the disease.
Encephalopathy (continued). "Nitrated albumin was found significantly increased in patients who developed moderate or severe encephalopathy compared to those who had a normal neurological evolution or developed mild encephalopathy." (PMID 25685254, 2015). "Furthermore, the presence of encephalopathy was associated with elevated levels of direct and total bilirubin, prolonged PT and PTT, increased INR, and decreased hemoglobin and albumin levels." (PMID 39011425, 2024). "Although Child–Pugh class is a well‐known method of evaluating the liver function, it consists of five variables, including serum albumin, total bilirubin and prothrombin time with cutoff values, and subjective assessments such as the presence of hepatic ascites and encephalopathy." (PMID 37987139, 2023). "POD incidence was higher in patients with signs of more severely compromised hepatic function (lower sodium and higher bilirubin levels, history of encephalopathy), poor nutritional status (lower albumin) and who were more frequently admitted to hospital or on life support prior to LT." (PMID 32974861, 2020). "The bilirubin-albumin ratio is a useful predictor for bilirubin encephalopathy." (PMID 31950971, 2020). "Although the bilirubin/albumin ratio is not a better predictor of bilirubin encephalopathy than total serum bilirubin, it helps identify infants at risk for neurotoxicity at low total bilirubin due to a low serum albumin concentration." (PMID 33033449, 2020). "Child-Pugh score, Model for the End-Stage Liver Disease (MELD) score, and their components (i.e., bilirubin, albumin, prothrombin time or international normalized ratio, creatinine, encephalopathy, and ascites) are considered as the major predictors for the survival of liver cirrhosis." (PMID 25810714, 2015). "Albumin dialysis was associated with a significant improvement in the degree of hepatic encephalopathy (p = 0.02), and no encephalopathy was present after treatment in five of the eight episodes." (PMID 19175915, 2009). "Ifosfamide was not used initially as his low serum albumin would have increased the risk of ifosfamide-induced encephalopathy." (PMID 18353189, 2008). "Therefore, in our study, we developed the TAI score, hypothesizing whether we could predict encephalopathy by using numerical laboratory parameters (total bilirubin, albumin, and INR) already included in the Child-Pugh score." (PMID 38496192, 2024). "Compared to Child-Pugh classification, which scores clinical measures including encephalopathy, ALBI only scores objective values (albumin and bilirubin)." (PMID 31681607, 2019). "The mean values of the patients were as follows: Total Bilirubin: 31 mg/dl, AST: 766U/L, ALT: 787U/L, INR: 3.2, albumin: 3 gr/dl, MELD score: 31.5, encephalopathy stage: 2.5." (PMID 29201697, 2015). "The use of albumin in paracentesis was associated with significantly reduced risk of paracentesis-induced circulatory dysfunction (OR 0.26 95%, CI 0.08–0.93) and there was a nonsignificant difference in death, encephalopathy, hyponatraemia, readmission, and renal impairment." (PMID 24222902, 2013). "We could not find any study in the literature relating laboratory values (total bilirubin, albumin, and INR) to encephalopathy." (PMID 38496192, 2024). "The ALBI grade, including both albumin and bilirubin levels, has been proven to be as effective as the Child–Pugh grade when assessing hepatic function in HCC patients without the need for subjective parameters such as ascites and encephalopathy." (PMID 37370766, 2023). "Also, the amount of hemoglobin and albumin in patients with encephalopathy was significantly lower than in patients without this disorder." (PMID 39011425, 2024). "Our patient, however, demonstrated compromised liver function as evidenced by a Child-Pugh score of 11 points (class C) with a total bilirubin of 3.4 mg/dL, albumin of 1.94 g/dL, international normalized ratio of 2.18, lack of ascites, and the grade 2+ encephalopathy with behavioral changes." (PMID 33655160, 2019).
Cognitive impairment (130 papers, 2014 to 2026). Abnormal cognition is characterized by deficits in thinking, reasoning, or remembering. "This study also found that albumin is a potentially modifiable risk indicator for cognitive impairment." (PMID 41346383, 2025). "In previous meta-analysis studies on orthopedic procedure, age, cognitive impairment, cerebrovascular disease, laboratory values such as total albumin, and surgery-related variables were identified as risk factors for POD, which is consistent with our study." (PMID 40168626, 2025). "In this study, longer hospital stays, a lower BMI on admission, cognitive impairment, and lower albumin levels on admission were associated with higher mortality rates." (PMID 39768438, 2024). "A previous seven-year retrospective cohort study among 1,800 subjects showed that relatively low serum albumin levels at baseline (< 40.5 g/L) were associated with an increased risk of mild cognitive impairment (HR: 2.18, 95% CI: 1.67–2.82)." (PMID 39206288, 2024). "When albumin was converted from a continuous variable to a categorical variable (quartiles), individuals in the highest quartile (Q4) had a 35% lower risk of cognitive impairment compared to those in the lowest albumin quartile (Q1)." (PMID 38409895, 2024). "Hazard ratios for the combined associations of plasma albumin and cognitive impairment status with all-cause mortality (N = 1858)." (PMID 39114122, 2024). "The findings of the study revealed that higher levels of serum albumin were associated with a reduced risk of cognitive impairment." (PMID 38409895, 2024). "Cohort studies have also suggested that low serum albumin is associated with increased odds of cognitive impairment and AD in the elderly population." (PMID 39206288, 2024). "In fact, urinary albumin/creatinine ratios of 30–299 and ≥300 mg/g were associated independently with 31% and 57% higher risks of cognitive impairment, respectively, relative to individuals with albumin/creatinine ratios lower than 10 mg/g." (PMID 39335505, 2024). "Previous investigation revealed the association between the lower levels of total protein and albumin and cognitive impairment in AD patients, and these reduced protein levels were identified as independent risk factors for rapid cognitive decline." (PMID 38515521, 2024). "Factors assessed included age, sex, body mass index (BMI), cognitive impairment, fracture type, surgical timing, length of hospital stay, implant type, preoperative hemoglobin/albumin/white blood cell levels, and Geriatric Nutritional Risk Index (GNRI)." (PMID 39768438, 2024). "Higher WBC (OR, 0.43; 95% CI, 0.19–0.98) and serum albumin (OR, 0.43; 95% CI, 0.36–1.05) were linked to a lower risk of cognitive impairment after adjustment." (PMID 37889501, 2023). "Our results indicated that participants with a higher albumin level had a lower risk of cognitive impairment." (PMID 36864383, 2023). "The association between protein with mild cognitive impairment and frailty was reported in four studies, and all found that low serum albumin was significantly associated with mild cognitive impairment and frailty." (PMID 36497797, 2022). "In the case of albumin, the obtained results are consistent with other data from studies in people 65+, which indicated that a low albumin concentration is a risk factor for cognitive impairment." (PMID 35458142, 2022). "Two cross-sectional studies reported that low serum albumin was significantly associated with mild cognitive impairment." (PMID 36497797, 2022). "According to the tools and thresholds used, the level of impairment in the domains explored by the geriatric parameters varied from 9% (cognitive impairment) to 66% (weight loss and albumin <35 g/L)." (PMID 35267412, 2022). "Despite many previous studies showing a significant association between serum albumin and cognitive impairment, relatively little work has been conducted to address the longitudinal association between serum albumin and cognitive impairment." (PMID 35160273, 2022).
Cognitive impairment (continued). "Results from two cross-sectional studies supported the evidence of low serum albumin being significantly associated with mild cognitive impairment." (PMID 36497797, 2022). "Several mechanisms have been proposed to explain the effects of serum albumin on patients with mild cognitive impairment risk." (PMID 36497797, 2022). "Recent studies have shown that a higher albumin level was associated with a lower risk of cognitive impairment." (PMID 34880747, 2021). "For instance, low serum ALB was found to be independently associated with increased odds of cognitive impairment in the elderly population." (PMID 33716920, 2021). "The results suggested that age, gender, serum albumin, and cognitive impairment were associated with AP occurrence." (PMID 32049822, 2020). "Subsequently multiple logistic regression analysis was conducted to investigate the risk factors for AP, including age, gender, serum albumin, cognitive impairment, and activities of daily living (ADL)." (PMID 32049822, 2020). "The results suggested that serum albumin, cognitive impairment, and ADL were associated with UR occurrence." (PMID 31192952, 2019). "Low serum albumin is associated with increased odds of cognitive impairment in the elderly, and both plasma and CSF albumin oxidation are higher in AD patients compared to healthy controls." (PMID 31681137, 2019). "Low albumin levels are associated with an increased risk of cognitive impairment." (PMID 41346383, 2025). "The utilization of these statistical methods allows for a nuanced analysis of the associations, offering valuable insights into the dose–response relationship between albumin levels and mortality risk, as well as the complex interplay between cognitive impairment and plasma albumin concentrations." (PMID 39114122, 2024). "There are several plausible mechanisms through which serum albumin may be associated with cognitive impairment in older adults." (PMID 38409895, 2024). "Recent studies have shown that higher albumin levels are associated with a lower risk of cognitive impairment, suggesting that maintaining high levels of albumin may benefit cognitive function in older adults." (PMID 39206308, 2024). "A nationally representative population-based study, involving 1,752 adults aged 65 and above who participated in the Health Survey for England 2000, revealed that low serum albumin levels were independently associated with an increased probability of cognitive impairment." (PMID 39114530, 2024). "Low serum albumin has been reported to be associated with cognitive impairment." (PMID 39358810, 2024). "Findings revealed a trend of significant association between low levels of B vitamins (folate and vitamin B12), vitamin D, vitamin A, vitamin E, omega 3 fatty acid, and albumin, and high homocysteine levels in blood with an increased risk of mild cognitive impairment among older adults." (PMID 36497797, 2022). "In conclusion, our findings suggest that elevated AST to ALT ratio and decreased levels of albumin and plasma triglyceride are associated with cognitive impairment, supporting the hypothesis that liver function alterations are involved in AD pathogenesis." (PMID 36313027, 2022). "From the present results it can be concluded that increased serum concentrations of vitamin A, vitamin D, TTR, albumin, Se and UA could act as a protective factor against cognitive impairment, whereas higher BMI could act as a risk factor." (PMID 35686024, 2022). "Further longitudinal studies to overcome the critical limitations of the current analysis are required to determine whether lower serum albumin levels are at greater risk of developing cognitive deficits in the older population." (PMID 35160273, 2022). "Taken together, the lower levels of ALB reported in this study may indicate an increased risk of cognitive impairment." (PMID 36313027, 2022).
Cognitive impairment (continued). "Notably, low levels of blood albumin in elderly persons is implicated in cognitive impairment, and evidently decreased blood albumin-Aβ complex is found in AD." (PMID 34454574, 2021). "This association of cognitive impairment with serum albumin and hemoglobin levels may be explained by certain pathophysiological mechanisms." (PMID 33028210, 2020). "This retrospective study found that serum albumin and cognitive impairment could be risk factors for AP in patients receiving post-operative surgery of femoral neck and trochanteric fractures." (PMID 32049822, 2020). "The present retrospective study has suggested that the serum albumin, cognitive impairment as well as ADL could be risk factors for UR in patients receiving postoperative surgery of femoral neck and trochanteric fractures." (PMID 31192952, 2019). "Furthermore, another study involving 1800 Chinese older adults aged 60 and above at baseline reported that lower serum albumin concentrations may serve as an independent risk factor for mild cognitive impairment in the elderly." (PMID 38409895, 2024). "While the fundamental mechanism underlying the correlation between serum albumin and cognitive function remains unidentified, insights from a limited clinical sample suggest a potential association between decreased serum albumin concentration and cognitive impairment." (PMID 39114530, 2024). "This study investigates the association between the blood urea nitrogen to albumin ratio (BAR) and cognitive impairment in PD patients, aiming to identify BAR as a potential biomarker for early detection and monitoring of cognitive decline." (PMID 41586088, 2025). "The urine albumin-to-creatinine ratio (UACR), a marker of kidney and vascular health, has been associated with systemic dysfunction, yet its association with cognitive impairment remains underexplored." (PMID 40323962, 2025). "A significant interaction effect was observed between a more severe cognitive impairment (i.e., MoCA <24) and CSF/serum albumin levels (F = 3.464, p = 0.034)." (PMID 39992249, 2025). "Univariate analysis identified age, BMI, cognitive impairment, albumin level, and GNRI as statistically significant predictors." (PMID 39768438, 2024). "In the unadjusted model, albumin was found to be negatively correlated with cognitive impairment (OR: 0.52, 95%CI: 0.38–0.72, P < 0.05)." (PMID 38409895, 2024). "In terms of biochemical markers, individuals with cognitive impairment demonstrated reduced concentrations of ALB, ALT, and SCr, alongside elevated levels of ALP, AST/ALT ratio, GGT, and TC." (PMID 39042647, 2024). "In the univariate analysis, age, BMI, length of hospital stay, cognitive impairment, albumin level on admission, and GNRI were found to be significantly associated with overall survival." (PMID 39768438, 2024). "Participants with both vitamin D deficiency and high hs-CRP were more likely to be older, illiterate, ADL impaired, cognitive impaired, had lower albumin, and had higher fasting blood glucose." (PMID 38302956, 2024). "The mechanism of the effect of serum albumin on reducing cognitive disorders has been attributed to the combination with beta-amyloid." (PMID 38799151, 2024). "Albumin levels and lymphocyte counts were negatively correlated with the severity of cognitive impairment." (PMID 39398776, 2024). "The power achieved for each variable was as follows: age (0.7661), BMI (0.9826), length of hospital stay (0.9156), cognitive impairment (0.9858), albumin level (0.982), and GNRI (0.9998)." (PMID 39768438, 2024). "The powers for BMI, cognitive impairment, albumin level, and GNRI were all >0.98, indicating that the sample size was sufficient to detect significant differences in survival outcomes." (PMID 39768438, 2024). "This study identified several prognostic factors for survival in patients aged ≥90 years with PFFs, including BMI, cognitive impairment, albumin level, and GNRI." (PMID 39768438, 2024).
Cognitive impairment (continued). "The cognitive impairment group exhibited a lower level of albumin (4.1 ± 0.3 g/dL) compared to the normal cognitive function group (4.2 ± 0.3 g/dL)." (PMID 38409895, 2024). "The high post hoc power achieved for the key prognostic factors (age, BMI, cognitive impairment, albumin level, and GNRI) supports the reliability of the study’s findings." (PMID 39768438, 2024). "It has been shown that β‐amyloid deposition is an important factor in the development of Alzheimer's disease and cognitive impairment, and serum albumin can bind to β‐amyloid and is an important regulator of β‐amyloid clearance." (PMID 39262164, 2024). "The model contained six predictors, including age, history of arrhythmia, history of mental illness or cognitive impairments, albumin levels, coagulation function, and surgical Apgar score." (PMID 38755693, 2024). "Abnormal cerebrospinal fluid (CSF)/serum albumin ratio (Qalb) levels have been observed in patients with cognitive impairment." (PMID 38756533, 2024). "A low BMI, cognitive impairment, low albumin levels, and lengthy hospital stays were significantly associated with increased mortality rates." (PMID 39768438, 2024). "We investigated alterations in performance of machine learning-based assessment of cognitive impairment when including and excluding serum albumin levels, a parameter indicative of nutritional status." (PMID 39114530, 2024). "Albumin levels were highest in the group with mild cognitive impairment (p=0.024) compared to the other two groups." (PMID 39398776, 2024). "Interestingly, changes in albumin levels have been independently linked to both aging and neurodegeneration, wherein situations of low serum albumin levels can be associated with an increased risk of cognitive impairment among the elderly population, possibly via increasing Aβ deposition." (PMID 38069410, 2023). "In this work, we successfully synthesized minocycline-loaded albumin nanoparticles and showed improvement in cognitive deficits as well as long-term neuroprotective effects with a single dose administration in blast TBI." (PMID 36979212, 2023). "The effect of serum albumin on cognitive impairment indicates nutritional status as a mitigating factor." (PMID 37889501, 2023). "Considering that both plasma FIB and albumin are good biomarkers of inflammation and closely related to cognitive impairment." (PMID 37576498, 2023). "Exercise in six months, higher albumin and HDL levels were significantly associated with a lower risk of cognitive impairment." (PMID 36864383, 2023). "A minority of previous clinical studies have included biochemical BBB leakage parameter in their data collection, with findings of correlation between CSF-albumin ratio and leakage rate in abnormal white matter areas and hippocampus in cognitive impairment." (PMID 37710058, 2023). "More patients with cognitive impairment and lower level of albumin were also revealed in the died (26 (30.6%) vs 57 (18.6%); 39.40 ± 3.68 vs 41.36 ± 2.86, respectively)." (PMID 37347299, 2023). "Patients with higher NIHSS scores (3 vs. 1, P = 0.004) and lower levels of albumin (37.31 ± 3.83 vs. 39.23 ± 3.33, P = 0.012) were more likely to experience cognitive impairment." (PMID 37881309, 2023). "Serum albumin has a high antioxidant function, and a reduction in its amount contributes to the oxidation/antioxidation imbalance and cognitive impairment." (PMID 36497797, 2022). "Lower albumin levels interfere with the adequate delivery of blood to the central nervous system and can lead to cognitive impairment." (PMID 36497797, 2022). "Body mass index, cognitive impairment (mini-mental state examination score), serum albumin, and hemoglobin were also significant predictors of mortality." (PMID 35053493, 2022).